SDC4 (syndecan 4)
Diseases named in the same sentence as SDC4 in open-access papers (continued):
Sharing a sentence is not in itself a finding about the gene and the disease.
lung carcinoma (6 papers, 2012 to 2024). "Preliminary results suggest that OA treatment decreases SDC4 expression and enhances lipid peroxidation levels, indicating its potential as a therapeutic method for lung cancer treatment." (PMID 39400975, 2024). "In conclusion, our study reveals the role of OA in inhibiting SDC4 expression and inducing ferroptosis in lung cancer cells." (PMID 39400975, 2024). "To investigate the anticancer effect and mechanism of OA on lung cancer, we first stimulated lung cancer cells with OA in vitro and observed its changes and further analyzed the role of ferroptosis, the SDC4 gene, and the glutathione peroxidase 4 (GPX4)/ACSL4 signaling pathway." (PMID 39400975, 2024). "SDC4 is involved in tumor growth as the lung cancer tumor size decreases in SDC4 KO mice." (PMID 39400975, 2024). "SDC4 participates in tumor growth as the size of lung carcinoma tumors was reduced in SDC4 KO mice." (PMID 34282767, 2021). "Therefore, whether SDC4 can participate in lung cancer treatment by inducing ferroptosis urgently needs a more precise analysis." (PMID 39400975, 2024). "The results showed that OA could inhibit the proliferation and migration of A549 cells and H1299 cells, SDC4 was a potential therapeutic target of OA against lung cancer, and OA treatment significantly inhibited the expression of SDC4 in A549 cells and H1299 cells." (PMID 39400975, 2024). "In lung cancers, fusions with CD74 (83/216, 38.4%), EZR (28/216, 13.0%), SDC4 (26/216, 12.0%), and SLC34A2 (26/216, 12.0%) were highly frequent." (PMID 36369474, 2022). "Similar cooperation was found by silencing techniques between syndecan-2 and -4 in actin stress fibre formation in lung cancer cell lines P29 and LM66-H11, or between syndecan-1 and syndecan-4 in the migration of dendritic cells after their phospholipid induced maturation." (PMID 22745764, 2012). "This study confirmed that OA could inhibit SDC4 expression and promote the occurrence of ferroptosis in A549 cells and H1299 cells through the GPX4/ACSL4 pathway, providing an effective basis for the use of drugs targeting ferroptosis in lung cancer treatment." (PMID 39400975, 2024).
renal cell carcinoma (6 papers, 2014 to 2022). "Up-regulation of syndecan-4 is associated with the development and metastasis of renal cell carcinoma, possibly by increasing the cell migratory potential and survival through integrin-mediated signaling." (PMID 25549223, 2014). "SDC4 upregulation increased the risk of renal cell carcinoma metastasis." (PMID 36199068, 2022). "Syndecan-4 has also been associated with the metastatic phenotype; analyses of renal cell carcinoma samples and the highly metastatic tumor cell line KP1 have revealed an association between aggressive phenotype and high expression of tissue transglutaminase (TG2) and syndecan-4." (PMID 26558271, 2015). "In contrast, a study utilizing data from the Human Protein Atlas dataset assigned a positive prognostic value to high syndecan-4 protein expression in renal cell carcinoma." (PMID 33810567, 2021). "A study demonstrated that metastatic Caki-1 and ACHN cells (human renal adenocarcinoma) expressed higher levels of syndecan-4 mRNA than primary renal cell carcinoma cell lines." (PMID 33810567, 2021). "The authors concluded that upregulation of syndecan-4 mRNA plays an important role in the development of renal cell carcinoma and advanced forms of the disease with metastasis." (PMID 33810567, 2021). "High SDC4 expression determines increased patient survival in renal cell carcinoma." (PMID 34282767, 2021). "SDC4 also plays a role in the occurrence and metastasis of renal cell carcinoma." (PMID 32503508, 2020).
cardiac hypertrophy (5 papers, 2011 to 2025). "Expression of B-type natriuretic peptide (BNP), which has been shown to be regulated by the transcription factor NFAT and associated with myocardial hypertrophy, was attenuated in syndecan-4−/−-AB compared to WT-AB." (PMID 22164265, 2011). "A double knockdown of α11 integrin and syndecan-4 was demonstrated to prevent cardiac hypertrophy in aortic-banded rats, whereas knockdown of α11 integrin alone was unable to prevent cardiac hypertrophy." (PMID 40869375, 2025). "Studies of constitutive syndecan-4 knock-out (Sdc4-KO) mice suggest that syndecan-4 regulates cardiac hypertrophy, however, its specific role in cardiomyocyte remodelling has been difficult to tease out." (PMID 36205855, 2022). "In this study, we show that syndecan-4 is essential for development of concentric myocardial hypertrophy by acting as a scaffolding protein for mechanical stretch-induced activation of the calcineurin-NFAT pathway." (PMID 22164265, 2011). "Expression of α-skeletal actin, previously shown to correlate with myocardial hypertrophy was lower in syndecan-4−/−-AB than in WT-AB." (PMID 22164265, 2011). "In summary, our data show that syndecan-4 is essential for development of compensatory myocardial hypertrophy in the pressure overloaded myocardium." (PMID 22164265, 2011). "Patients with aortic stenosis exhibited decreased pS179-syndecan-4/syndecan-4 ratios, indicating a direct relevance to human myocardial hypertrophy." (PMID 22164265, 2011). "In conclusion, our data indicate that syndecan-4 is a scaffolding protein for activation of calcineurin-NFAT signaling and development of concentric myocardial hypertrophy during pressure overload, both in mice and man." (PMID 22164265, 2011). "Echocardiographic, histochemical and cardiomyocyte size measurements showed that syndecan-4−/− mice did not develop concentric myocardial hypertrophy as found in wild-type mice, but rather left ventricular dilatation and dysfunction following pressure overload." (PMID 22164265, 2011).
dilated cardiomyopathy (5 papers, 2016 to 2025). Cardiomyopathy which is characterized by dilation and contractile dysfunction of the left and right ventricles. "Along the differentiation trajectory, early DEG were associated with ECM-receptor interaction and TGFβ signaling as well as focal adhesion, while late in this trajectory expressed genes were associated with dilated cardiomyopathy, syndecan 4 pathway, translation and the BDNF signaling pathway." (PMID 35641541, 2022). "It was previously reported that, in subjects with dilated cardiomyopathy due to other etiologies, serum levels of syndecan-4 correlated negatively with LVEF and diastolic diameters." (PMID 29232393, 2017). "Mice with deleted PECAM-1, Syndecan-1, and Syndecan-4 are healthy and fertile, although PECAM-1 knockouts suffer from dilated cardiomyopathy and systolic dysfunction." (PMID 27027326, 2016).
fibrosarcoma (5 papers, 2011 to 2023). A malignant mesenchymal fibroblastic neoplasm affecting the soft tissue and bone. "This proteoglycan is often overexpressed in adenocarcinoma cells, whereas mesothelioma and fibrosarcoma cells express syndecan-2 and syndecan-4 more abundantly." (PMID 24392351, 2013). "Overexpression of syndecan-1 also influences syndecan-4 expression, however, in a more variable manner as it is upregulated in MM cells but downregulated in fibrosarcoma cells." (PMID 21731601, 2011). "Overexpression of syndecan-1 resulted in a downregulation of syndecan-2 and upregulation of syndecan-4 in epithelioid mesothelioma cells, whereas in epithelioid fibrosarcoma cell line syndecan-2 was upregulated, and in a sarcomatoid fibrosarcoma cell line syndecan-4 was downregulated." (PMID 24392351, 2013).
germ cell tumor (5 papers, 2013 to 2021). A benign or malignant, gonadal or extragonadal neoplasm that originates from germ cells. "Reduced SDC4 expression is associated with reduced metastatic potential in testicular germ cell tumors." (PMID 34282767, 2021). "Reduced tumour cell associated staining for syndecan-4 was observed in nonseminomatous germ cell tumours (NSGCTs) compared to seminomas." (PMID 23844358, 2013). "The same results were observed in non-seminomatous germ cell tumors, in which immunostaining for SDC4 in advanced stages was reduced." (PMID 34445387, 2021). "Reduced levels of SDC-4 in non-seminomatous germ cell tumors are related to their metastatic potential, whereas stromal staining of SDC-4 in testicular germ cell tumors is correlated with angiogenesis." (PMID 24551591, 2014).
lung adenocarcinoma (5 papers, 2017 to 2024). A carcinoma that arises from the lung and is characterized by the presence of malignant glandular epithelial cells. "In contrast, SDC4 promotes cell migration and invasion of A549 lung adenocarcinoma cells both in wound healing and chemotaxis assays and SDC4 positively regulates TGFβ1-mediated EMT via Snail." (PMID 34282767, 2021). "SDC4 is known to positively regulate TGFβ1-induced EMT (via Snail) in lung adenocarcinoma cells, whilst SDC4-signalling negatively regulates the production of TGFβ1 (reported in the kidneys of SDC4 KO mice)." (PMID 34282767, 2021). "Moreover, in thyroid cancer and lung adenocarcinoma, the SDC4-mediated epithelial-mesenchymal transformation process was found to be closely related to the invasion and migration of tumor cells." (PMID 37954130, 2023). "Nevertheless, SDC4, although less explored in the context of EMT, has been reported to positively regulate TGF-β1-induced EMT in lung adenocarcinoma cells." (PMID 38683136, 2024).
metabolic syndrome (5 papers, 2021 to 2025). A cluster of metabolic risk factors for CARDIOVASCULAR DISEASES and TYPE 2 DIABETES MELLITUS. "Although single nucleotide polymorphisms (SNPs) of the Sdc4 gene have been identified linking to metabolic syndromes, its specific function in adipose tissue remains obscure." (PMID 40180176, 2025). "Single nucleotide polymorphism (SNP) of the human Sdc4 gene is related to altered fat storage, energy expenditure, insulin sensitivity, and metabolic syndrome." (PMID 40180176, 2025). "During DIO, Sdc4 deletion contributes to dyslipidemia, hyperglycemia and insulin resistance, as well as increased adipocyte size and macrophage infiltration." (PMID 40497936, 2025). "We then tested whether SDC4 polymorphisms are related to the metabolic syndrome (MetS) in humans." (PMID 37461091, 2023).
resistant hypertension (5 papers, 2020 to 2025). "Although these include cohorts with relatively few patients, circulating levels of syndecan-4 are increased after acute MI, resistant hypertension and chronic heart failure." (PMID 37189684, 2023). "With the fact that increased Sdc4 and Mmp9 have been shown to contribute to obesity-related disorders such as resistant hypertension and atrial fibrillation, the detrimental effects of Mmp9 may be at least partially mediated through its induction on Sdc4 shedding." (PMID 40180176, 2025). "Thus, SDC4 might represent an encouraging biomarker for endothelial dysfunction in patients with resistant hypertension, which needs further evaluation in larger cohorts." (PMID 32971813, 2020). "Thus, SDC4 might be a potential marker for endothelial dysfunction in patients with resistant hypertension." (PMID 32971813, 2020).
Sepsis (5 papers, 2017 to 2024). Sepsis is defined as life-threatening organ dysfunction caused by a dysregulated host response to infection. "Syndecan-4-deficient mice have a high mortality, as determined using mouse models of sepsis induced by intraperitoneal administration of LPS, and they show severe liver failure in response to concanavalin A, suggesting an important role of syndecan-4 in limiting inflammation." (PMID 28467516, 2017). "Interestingly, several of the genes linked to glucocorticoid signaling (Arl4d, Cdkn1a, Ddit4, Fkbp5, Gjb6, Il6ra, Klf15, Nfkbia, Rhob, Sdc4, Sgk1, Sult1a1, Tob2, Wipf3) and apoptotic process were still upregulated 4 days post-sepsis." (PMID 31278440, 2019). "Artificial intelligence systems identified eight out of twenty novel genetic markers (SDC4, CLEC5A, TCN1, MS4A3, HCAR3, OLAH, PLCB1, and NLRP1) that help predict sepsis severity or mortality." (PMID 33692779, 2021). "Since SDC1 and SDC4 are known to influence the cargo of EVs, we cannot exclude the impact of SDC2 on the composition of MSC‐derived EVs and this influence on sepsis pathobiology." (PMID 34355516, 2022).
viral infection (5 papers, 2016 to 2022). "Furthermore, we carried out the survival rate assays, and found that SDC4-deficient mice were more resistant to virus infection, compared with the wild-type control." (PMID 27279133, 2016). "Flag-RIG-I(N) overexpression inhibited VSVΔM51-GFP replication, which is consistent with its antiviral role, whereas co-expression with SDC4 rendered the cells more susceptible to viral infection, suggesting that SDC4 negatively regulates the RIG-I-mediated antiviral signalling pathway." (PMID 27279133, 2016). "We show that SDC4 expression is induced by viral infection, but it functions as a negative regulator that attenuates RIG-I activity, thereby maintaining antiviral signalling homeostasis in a feedback regulatory manner." (PMID 27279133, 2016). "Collectively, these findings suggest that SDC4 expression is stimulated by viral infection in a feedback manner." (PMID 27279133, 2016). "The expression levels of Sdc4 mRNA and SDC4 protein were significantly increased in a time-dependent manner on virus infection." (PMID 27279133, 2016). "In this study, we evaluated the lipocalin-2 (LIP2) and syndecan-4 (SYN4) levels in children who were hospitalized for radiologically confirmed CAP in order to differentiate bacterial from viral infection." (PMID 27439403, 2016). "For example, CALR suppresses IFN-α production and antiviral activity in the context of hepatitis B virus infection, ERAP1 induces cleavage of cytokine receptors, and syndecan-4 (SDC4) negatively regulates retinoic acid-inducible gene I (RIG-I)-mediated signalling during virus infection." (PMID 35727847, 2022). "To do so, we measured the dynamics of Sdc4 mRNA and SDC4 protein expression on virus infection." (PMID 27279133, 2016). "To determine whether the Sdc4 knockout affects the type I IFN response after virus infection, we infected Sdc4–/– mouse embryonic fibroblasts (MEFs) with SeV and measured the expression levels of type I IFN-dependent genes." (PMID 27279133, 2016). "Meanwhile, the mRNA transcript and protein levels of SDC4 are increased on virus infection." (PMID 27279133, 2016). "On the basis of our results, we propose the following working model to illustrate how SDC4 could negatively regulate RIG-I-mediated type I IFN signalling on viral infection." (PMID 27279133, 2016). "On the other hand, SDC4, PIK3CA, and IQGAP1 genes showed upregulated expression upon viral infection, and after mimic transfection and infection, their expression levels were decreased in hNP cells." (PMID 31578247, 2019). "SDC4 likely promotes redistribution of RIG-I and CYLD in a perinuclear pattern post viral infection, and thus enhances the RIG-I–CYLD interaction and potentiates the K63-linked deubiquitination of RIG-I." (PMID 27279133, 2016). "Coincident with enhanced IRF3 signalling and IFN-β production, Sdc4 mRNA and SDC4 protein were significantly increased in HEK293 cells and HepG2 cells on virus infection." (PMID 27279133, 2016). "Similarly, SDC4, PIK3CA, and CAV1 genes showed upregulated expression upon viral infection, and after miR-124-3p mimic transfection and infection, their expression levels were decreased in hNS1 cells." (PMID 31578247, 2019). "In addition, membrane fraction assays showed that SDC4, RIG-I and CYLD accumulated at membrane fraction on virus infection." (PMID 27279133, 2016). "Notably, we found that the induced endogenous SDC4 by viral infection is mainly overlapped with TGN-GFP marker (TGN: the trans-Golgi network) and accumulated in perinuclear region, suggesting that the perinuclear-localized SDC4 is de novo synthesized." (PMID 27279133, 2016). "Consistently, endogenous CYLD was detected in the SDC4 complex in the absence of viral infection." (PMID 27279133, 2016).
aortic stenosis (4 papers, 2011 to 2023). Aortic valve stenosis is a aortic valve disease caused by the incomplete opening of the aortic valve. "Finally, patients with hypertrophic myocardium due to aortic stenosis had increased syndecan-4 levels with decreased pS179 which was associated with increased NFAT activation." (PMID 22164265, 2011). "In aortic stenosis patients and mouse models of myocardial infarction and pressure overload, a role for full-length syndecan-4 in stress-induced fibrosis has been shown." (PMID 28534817, 2017). "Shed syndecan-4 is found in myocardial tissue biopsies from heart failure patients and in the coronary sinus of patients with aortic stenosis, suggesting shedding from cardiac cells in response to persistent mechanical stress." (PMID 28534817, 2017). "Syndecan-4 levels are increased in the hypertrophic myocardium of patients with aortic stenosis, and increased syndecan-4 levels have also been demonstrated in the post-infarcted heart." (PMID 25410619, 2014). "In order to demonstrate a direct relevance to human heart disease, we examined levels of syndecan-4 and syndecan-4 phosphorylation in biopsies taken peroperatively from patients with hypertrophic myocardium due to aortic stenosis and controls." (PMID 22164265, 2011). "Moreover, the significantly reduced myocardial phosphorylation of S179-syndecan-4/total syndecan-4 ratios combined with increased NFAT activation found in patients with aortic stenosis indicates a direct relevance for this mechanism in human heart disease." (PMID 22164265, 2011). "To test whether circulating syndecan-4 originated from the heart, we used ELISA to measure the venous-arterial difference in serum from the coronary sinus, i.e., venous blood from the heart, and the radial artery, of aortic stenosis patients during open heart surgery." (PMID 37189684, 2023).
asthma (4 papers, 2016 to 2025). "It has been reported that polyclonal antibodies prepared using the extracellular segment of SDC4 (N93-V121) as the antigen achieved the same relief as knocking down SDC4 in experimental asthma and rheumatoid arthritis." (PMID 40747330, 2025). "In experimental asthma and rheumatoid arthritis, knocking down SDC4 can inhibit the inflammatory response and relieve the symptoms." (PMID 40747330, 2025). "Relatedly, syndecan 4 blocking antibodies inhibit the directional migration of B-cells in an asthma model, and B-cells from syndecan 4−/− mice also show impaired directional cell migration in an arthritis model." (PMID 35186924, 2022). "In contrast, blocking of SDC4 signaling with an antibody reduced eosinophilic airway inflammation in an asthma model using ovalbumin-sensitized mice." (PMID 29230082, 2017). "However, by increasing SDC4 levels on the cell surface, signaling might be enhanced leading to an exacerbation of asthma." (PMID 29230082, 2017).
endothelial dysfunction (4 papers, 2020 to 2022). In vascular diseases, endothelial dysfunction is a systemic pathological state of the endothelium (the inner lining of blood vessels) and can be broadly defined as an imbalance between vasodilating and vasoconstricting substances produced by (or acting on) the endothelium. "In summary, endothelial SIRT1-deficiency, a model of global endothelial dysfunction, leads to upregulation of syndecan-4 and release of its ectodomain, the loss of the EG through increased superoxide generation and induced NF-κB signaling." (PMID 32494847, 2020). "In addition, syndecan-4 ectodomain is highly upregulated in this model of global endothelial dysfunction." (PMID 32494847, 2020). "Due to its main location on the endothelial glycocalyx, SDC4 is affected by diseases exerting its main damage on the endothelium, like HTN and might serve as a predictor of endothelial dysfunction." (PMID 32971813, 2020).